LIMK2 (LIM domain kinase 2)
Description:
Serine/threonine-protein kinase that plays an essential role in the regulation of actin filament dynamics. Acts downstream of several Rho family GTPase signal transduction pathways. Involved in astral microtubule organization and mitotic spindle orientation during early stages of mitosis by mediating phosphorylation of TPPP. Displays serine/threonine-specific phosphorylation of myelin basic protein and histone (MBP) in vitro. Suppresses ciliogenesis via multiple pathways; phosphorylation of CFL1, suppression of directional trafficking of ciliary vesicles to the ciliary base, and by facilitating YAP1 nuclear localization where it acts as a transcriptional corepressor of the TEAD4 target genes AURKA and PLK1.
Tractability: Small molecule: a structure with a bound ligand is known; a high-quality ligand is known; it belongs to a druggable protein family. PROTAC: it is named in the literature on targeted protein degradation; ubiquitination databases record sites on it; its protein half-life has been measured; a small molecule that binds it is known.
Target class: Kinase; TKL protein kinase group; Protein Kinase; TKL protein kinase LISK family; TKL protein kinase LIMK subfamily; Enzyme
Chemical probes: TH257 (high quality), THNAN69 (high quality)
Gene: Protein-coding gene on chromosome 22 (31,212,193 to 31,280,964, forward strand). Ensembl gene ENSG00000182541.
Subcellular location: Cytoplasm, cytoskeleton, spindle; Cytoplasm, cytoskeleton, microtubule organizing center, centrosome; Cytoplasm (Isoform LIMK2a); Nucleus; Cytoplasm (Isoform LIMK2b); Cytoplasm, perinuclear region
Subcellular location (Human Protein Atlas): Nucleoplasm; Cytosol
Pathways (Reactome):
Developmental Biology: EPHB-mediated forward signaling; Sema4D induced cell migration and growth-cone collapse
Signal Transduction: RHO GTPases Activate ROCKs
Gene Ontology:
Molecular function: protein binding; protein serine kinase activity; protein serine/threonine kinase activity; ATP binding; protein kinase activity
Biological process: astral microtubule organization; establishment of vesicle localization; negative regulation of cilium assembly; positive regulation of protein localization to nucleus; protein phosphorylation; actin cytoskeleton organization
Cellular component: centrosome; cytosol; mitotic spindle; nucleoplasm; cytoplasm; nucleus; cis-Golgi network; perinuclear region of cytoplasm; spindle
Genetic constraint (gnomAD): Loss-of-function variants: 27 observed, 64.03 expected, observed/expected ratio (o/e) 0.42, 90% interval 0.31 to 0.58. The upper end of that interval is the gene's LOEUF score, 0.58, which puts it in group 2 of 6, group 1 being the genes least tolerant of losing a copy. Missense variants: 565 observed, 758.88 expected, observed/expected ratio (o/e) 0.74, 90% interval 0.69 to 0.8. Synonymous variants: 266 observed, 295.79 expected, observed/expected ratio (o/e) 0.9, 90% interval 0.81 to 1.
Homologues: Orthologues: macaque LIMK2 (98% identical), dog LIMK2 (95% identical), guinea pig LIMK2 (95% identical), pig LIMK2 (95% identical), rabbit LIMK2 (94% identical), mouse Limk2 (93% identical), rat Limk2 (93% identical), chimpanzee LIMK2 (89% identical), zebrafish limk2 (67% identical), tropical clawed frog limk2 (58% identical). Paralogues in human: LIMK1 (54% identical), LRRK2 (25% identical), TESK1 (22% identical), TESK2 (21% identical), TNNI3K (21% identical), BRAF (18% identical), RAF1 (18% identical), MAP3K9 (17% identical), KSR2 (17% identical), KSR1 (16% identical), MAP3K21 (16% identical), ARAF (16% identical), and 11 more.
Diseases named in the same sentence as LIMK2 in open-access papers:
LIMK2 is named in the same sentence as 48 diseases in open-access papers, as found by Europe PMC text mining. Sharing a sentence is not in itself a finding about the gene and the disease. The quoted sentences say what the papers report.
osteosarcoma (12 papers, 2017 to 2025). A usually aggressive malignant bone-forming mesenchymal neoplasm, predominantly affecting adolescents and young adults. "In this study, we reveal that STAT3 knockdown attenuates the expression of PD-L2, p-LIMK2 and p-cofilin in osteosarcoma, suggesting that VEGFR2 inhibition suppresses migration, invasion and PD-L2 expression by targeting the STAT3 and RhoA-ROCK-LIMK2 pathways." (PMID 33014879, 2020). "For the first time, we showed that BMPR2 was a positive regulator of LIMK2 in osteosarcoma cells." (PMID 28938584, 2017). "A smaller subfamily in this category includes the LIM domain kinase 2 (LIMK2), which is an important regulator of growth and invasion of several cancers, including pancreatic cancer, bladder cancer, osteosarcoma, and glioblastoma." (PMID 32859889, 2020). "Mechanistically, we found that LIM domain kinase 2 (LIMK2) was phosphorylated and activated by BMPR2 and that this event was crucial for activation of the BMPR2-mediated signal pathway in osteosarcoma cells." (PMID 28938584, 2017). "Regarding the management of osteosarcoma, preclinical studies have shown that apatinib promotes apoptosis and autophagy through VEGFR2/STAT3/BCL-2 signaling pathways in osteosarcoma cells, as well as attenuates invasion and migration through RhoA/ROCK/LIMK2 pathways." (PMID 36387068, 2022). "Moreover, BMPR2-depletion decreased osteosarcoma cell invasion and metastasis in vitro and in vivo by the inactivation of the RhoA/ROCK/LIMK2 pathway." (PMID 28938584, 2017).
breast carcinoma (10 papers, 2008 to 2023). "Although LIMK2 has been implicated in several cancer types, the role of LIMK2 in breast cancer is not fully understood." (PMID 34678587, 2022). "Although LIMK2 has been implicated in several different cancer types, the role of LIMK2 in breast cancer is not fully understood." (PMID 32859889, 2020). "LIMK1 and LIMK2 have been reported to be overexpressed in breast cancer, and there is growing evidence of their implication in molecular pathways with interactors linked to breast cancer tumorigenesis." (PMID 36899941, 2023). "Furthermore, by analyzing several publicly available breast cancer mRNA expression datasets, we found that increased LIMK2 expression was also associated with increased incidence of metastasis, recurrence, and death in breast cancer patients." (PMID 32859889, 2020). "Reciprocally, LIMK2 is required for AURKA-mediated cellular transformation in breast cancer, indicating that LIMK2 is a key oncogenic effector of AURKA in breast cancer malignancy." (PMID 36899941, 2023). "A migration screen based on a phagokinetic track assay identified SRPK1 as a determinant factor in breast cancer metastasis; and a separate study demonstrates that the LIM domain kinase 2 (LIMK2) promotes breast cancer metastasis through SRPK1 activation." (PMID 36895328, 2023). "As AURKA is well known for its implication in cancer development, its role in LIMK2 activation will be more extensively discussed in the breast cancer subsection." (PMID 36899941, 2023). "Because TNBC is an aggressive breast cancer subtype that currently lacks effective therapeutic approaches, we focused our studies with LIMK2 on TNBC." (PMID 32859889, 2020). "We found that LIMK2 was overexpressed in various breast cancer subtypes, including a substantial portion of TNBCs, using tissue microarrays." (PMID 32859889, 2020). "In immunohistochemical analysis, we found that LIMK2 expression was significantly higher in breast cancer samples, including those of TNBC, than in normal tissue." (PMID 32859889, 2020). "Our results point to a distinct function for LIMK1 and LIMK2 downstream of ROCK during breast cancer cell migration." (PMID 18852895, 2008). "To understand the role of LIMK2 in breast cancer, we first asked whether LIMK2 was overexpressed in breast cancer." (PMID 38137332, 2023). "However, previous studies have demonstrated that LIMK2 is correlated with poor prognosis in many cancers, including bladder cancer, breast cancer, and prostate cancer." (PMID 35273591, 2022). "We corroborated this finding using publicly available datasets to show that LIMK2 expression was higher in TNBC tumors compared to other breast cancer subtypes and to show that LIMK2 overexpression predicted increased incidence of metastasis, disease recurrence, and death in breast cancer patients." (PMID 32859889, 2020). "To understand the role of LIMK2 in breast cancer, we first asked whether LIMK2 is overexpressed in breast cancer." (PMID 32859889, 2020). "To test this, we used a small-molecule LIMK2 inhibitor, LX7101 (Lexicon Pharmaceutical), to determine whether pharmacological inhibition of LIMK2 altered the metastatic properties of breast cancer cells." (PMID 32859889, 2020). "Indeed, LIMK1 and LIMK2 have been shown to be upregulated in breast cancer, gastric cancer, prostate cancer, and malignant melanoma cells, and they seem to be involved in multiple non-canonical signalling pathways that, when dysregulated, actively participate in tumorigenesis." (PMID 36899941, 2023). "We showed that like LIMK2, SRPK1 is overexpressed in several breast cancer subtypes compared to normal breast tissue." (PMID 32859889, 2020). "Further detailed characterization of these targets will likely reveal new functions of LIMK2 in TNBC, other subtypes of breast cancer, and other cancer types." (PMID 32859889, 2020).
breast carcinoma (continued). "We also found that similar to LIMK2, SRPK1 was overexpressed in TNBC compared to other breast cancer subtypes, and SRPK1 overexpression in breast cancer predicted increased incidence of cancer metastasis, recurrence, and death." (PMID 32859889, 2020). "Consistent with our results, analysis of multiple publicly available breast cancer mRNA expression datasets also showed significantly higher LIMK2 mRNA expression in TNBC (ERBB2/ER/PR negative) compared to breast cancer with other biomarker status 21–26." (PMID 32859889, 2020). "We found that single knockdown of LIMK1 or LIMK2 triggered a strong decrease (about 80%) in matrix degradation without affecting MT1-MMP levels or expression of the other LIMK isoform in MDA-MB-231 cells and BT-549 breast cancer cells." (PMID 27116935, 2016).
colorectal cancer (5 papers, 2018 to 2023). A primary or metastatic malignant neoplasm that affects the colon or rectum. "LIMK1 was reported to be overexpressed in colorectal cancer tissues and functioned as a competitive inhibitor of LIMK2 to promote the nuclear translocation of β-catenin, thus promoting tumor progression through activation of the Wnt/β-catenin pathway." (PMID 35350839, 2022). "Previous studies have demonstrated that low expression of LIMK2 in colorectal cancer enhanced the accumulation of β-catenin in the nucleus to activate Wnt signaling pathway and promote tumor progression, while high expression of LIMK2 inhibited the proliferation and migration of tumor cells." (PMID 37189142, 2023). "The imbalanced expression of LIMK1 and LIMK2 could promote β-catenin nuclear translocation and activate the wnt signaling pathway, thus leading to colorectal cancer progression." (PMID 36901953, 2023).
prostate carcinoma (5 papers, 2021 to 2024). A carcinoma that arises from epithelial cells of the prostate gland. "We have shown that LIMK2 levels increase with prostate cancer progression, with the highest levels in CRPC." (PMID 39334449, 2024). "PTEN, which is downregulated in prostate cancer, has been shown to be an LIMK2 substrate which phosphorylates it and participates in its degradation." (PMID 36899941, 2023). "For instance, LIMK2 downregulated NKX3.1 to increase the oncogenicity of castration-resistant prostate cancer, and overexpressed LIMK2 exhibited as a facilitator of triple-negative breast cancer metastasis by regulating SRPK1." (PMID 37189142, 2023). "LIMK1 and LIMK2 are overexpressed in prostate cancer and prostate cell lines, and numerous LIMK partners that are dysregulated in prostate cancer have been discovered over the last years." (PMID 36899941, 2023). "Upon hypoxia, in 22Rv1, PC-3, and LN95 prostate cancer cell lines, LIMK2 is upregulated and phosphorylates the phosphatase and TENsin homolog protein (PTEN) at five sites (Ser207, Ser226, Ser360, Ser361, and Ser362), causing its ubiquitination and degradation." (PMID 36899941, 2023). "The group of Shah has been particularly active in demonstrating the role played by LIMK2 in prostate cancer over the last years." (PMID 36899941, 2023). "Thus, LIMK2 inhibitor provides a powerful opportunity to rescue NKX3.1 loss, thereby preventing and/or delaying prostate cancer progression." (PMID 34066036, 2021). "Furthermore, the sequential treatment of prostate cancer cell line C4-2 with docetaxel, a well-established treatment for CRPC, and then with an LIMK2-specific inhibitor, resulted in a significant cellular death." (PMID 36899941, 2023).
triple-negative breast carcinoma (5 papers, 2020 to 2023). An invasive breast carcinoma which is negative for expression of estrogen receptor (ER), progesterone receptor (PR), and human epidermal growth factor receptor 2 (HER2). "LIMK2 expression is associated with metastatic spread in triple negative breast cancer." (PMID 35583632, 2022). "The inhibition of SRPK1 blocked the metastatic properties of TNBC cells, which led to the thought that LIMK2 promotes the metastatic progression of triple-negative breast cancer by activating SRPK1." (PMID 36899941, 2023). "Serine-arginine protein kinase 1 (SRPK1) has also been described as a target of LIMK2, and this connection plays a major role in triple negative breast cancer metastasis." (PMID 36899941, 2023). "Pharmacological inhibition of SRPK1 in triple negative breast cancer cell lines results in a reduced capacity for invasion and migration, supporting a link between SRPK1 and LIMK2 signalling in the context of metastatic spread in triple negative breast cancer." (PMID 35583632, 2022). "However, other results have shown that LIMK2 was overexpressed in triple-negative breast cancer (TNBC) and was necessary for facilitating metastasis." (PMID 38137332, 2023). "LIMK2 is overexpressed in triple-negative breast cancer (TNBC) and pharmacological inhibition, with LX7101 or TH-257, leads to the inhibition of the metastatic characteristics of TNBC cells (migration, invasion, actomyosin contractility, and extracellular matrix degradation)." (PMID 36899941, 2023). "LIMK1 and LIMK2 were also shown to interact with the membrane-anchored type-1 matrix metalloproteinase (MT1-MMP, or MMP14) in triple-negative breast cancer." (PMID 36899941, 2023).
neuroblastoma (4 papers, 2013 to 2023). Neuroblastoma (NB) is the most common solid, extracranial childhood tumor. "In this study, we report that LIMK2 acts as a survival factor in neuroblastoma cell lines to counteract the effect of diverse chemotherapeutic drugs and shed light on the signaling pathways that may associate LIMK2 with tumor cell resistance." (PMID 23991158, 2013). "Further studies are required to examine the relationship between LIMK2 expression and drug resistance in a broad panel of cell lines representative of high-risk neuroblastoma as well as in tumor samples from neuroblastoma patients taken before and after chemotherapy." (PMID 23991158, 2013). "Meanwhile, some findings suggest that LIMK2 expression is elevated in neuroblastoma cells resistant to microtubule-targeted drugs." (PMID 37894409, 2023). "Our results are consistent with a previous study showing that LIMK2 knockdown in neuroblastoma cells increased the sensitivity to microtubule-targeted drugs and caused enhanced apoptosis." (PMID 31319858, 2019). "We demonstrated that the endogenous LIMK2 and TPPP1 proteins interact in neuroblastoma cells, as previously demonstrated in HeLa cells overexpressing LIMK2 and TPPP1." (PMID 23991158, 2013). "Here, we report that depletion of LIMK2 sensitizes SHEP neuroblastoma cells to several microtubule-targeted drugs, and that this increased sensitivity correlates with enhanced cell cycle arrest and apoptosis." (PMID 23991158, 2013). "LIMK2 is highly expressed in vincristine- and colchicine-resistant neuroblastoma cell lines." (PMID 37894409, 2023). "The levels of LIM-kinase 2 (LIMK2) are increased in neuroblastoma cells selected for their resistance to microtubule-targeted drugs, suggesting that LIMK2 might be a possible target to overcome drug resistance." (PMID 23991158, 2013). "In summary, this study shows that high LIMK2 levels correlate with resistance to a wide range of chemotherapeutic drugs through different mechanisms of action and that LIMK2 down-regulation increases the sensitivity of neuroblastoma cells to these drugs." (PMID 23991158, 2013). "Interestingly, previous research showed that neuroblastoma cells selected for resistance to Vincristine had increased LIMK2 expression, while LIMK2 knockdown led to the formation of abnormal mitotic spindles and sensitized neuroblastoma cells to Vincristine and Vinblastine." (PMID 26540348, 2015). "In neuroblastoma cells selected for their resistance to vincristine and colchicine, expression of LIM kinase 2 (LIMK2) is significantly increased." (PMID 23991158, 2013). "The most exciting conclusion of our study is that LIMK2 is a common contributor to chemotherapeutic drug resistance, suggesting that combining specific LIMK2 inhibitors with certain chemotherapeutic agents may be an attractive strategy for the treatment of drug-resistant neuroblastomas." (PMID 23991158, 2013). "To corroborate the requirement for LIMK activity in neuroblastoma cells, we knocked down LIMK1 and LIMK2, either by combining two siRNA oligonucleotides (LIMK1+LIMK2) or using an siRNA oligonucleotide (panLIMK) that reduces expression of both proteins, in SK-N-AS and SK-N-SH cells." (PMID 26540348, 2015).
pancreatic cancer (4 papers, 2014 to 2020). "Another study showed that the selective LIMK2 inhibitor T56-LIMKi blocked pancreatic cancer xenograft growth in mice." (PMID 32859889, 2020). "For example, a previous study showed knockdown of LIMK2 reduced pancreatic cancer cell-induced angiogenesis." (PMID 32859889, 2020). "Research on zebrafish has confirmed that LIMK1 and LIMK2 lead to pancreatic cancer metastasis and angiogenesis." (PMID 29970879, 2018). "LIMK1 and LIMK2 are important for pancreatic cancer cell metastasis and tumor cell-induced angiogenesis." (PMID 27902487, 2017). "More specifically pancreatic cancer (Panc-1) was selected because LIMK2 was shown to be involved in tumor progression in this cell line." (PMID 25593987, 2014). "LIMK2 reportedly plays a role in tumor manifestation in pancreatic cancer, glioma and schwannoma cells." (PMID 25593987, 2014). "Here we report that T56-LIMKi is a highly specific inhibitor of LIMK2, and demonstrate its potency in inhibiting growth of pancreatic tumors in vitro and in vivo." (PMID 25593987, 2014). "Recent studies demonstrate an important role for both LIMK1 and LIMK2 in pancreatic tumor progression, cancer cell-induced angiogenesis, and metastasis formation." (PMID 25593987, 2014). "Therefore, to test the effect of our novel LIMK2 inhibitor on cell transformation in vivo, the model we chose was a mouse xenograft injected with Panc-1 cells (a similar experimental paradigm to the one we used to test Salirasib, another inhibitor of human pancreatic tumor growth)." (PMID 25593987, 2014).
bladder cancer (3 papers, 2019 to 2022). "In this study, we show ANXA2 and LIMK2 play oncogenic roles in mediation of the aggressiveness of bladder cancer cells." (PMID 31695759, 2019). "We next sought to determine whether the NUDT21-ANXA2/LIMK2-Wnt/NF-κB axis identified in BC cells is clinically relevant using 10 freshly prepared bladder cancer tissues." (PMID 31695759, 2019).
breast tumor (3 papers, 2016 to 2025). "All together, these data indicate that LIMK1 and LIMK2 are required for matrix proteolysis by breast tumor cells through control of MT1-MMP function." (PMID 27116935, 2016). "Our results suggest non-redundant roles for LIMK1 and LIMK2 in matrix degradation and invadopodial recruitment of Tks5 in breast tumor cells." (PMID 27116935, 2016).